TRPA1 (transient receptor potential cation channel subfamily A member 1)
Diseases named in the same sentence as TRPA1 in open-access papers (continued):
Sharing a sentence is not in itself a finding about the gene and the disease.
colitis (continued). "On the other hand, TRPA1 can also induce the inflammatory response via neurogenic inflammation: activation and sensitization of TRPA1 and release of substance P contribute to the initiation and development of colitis in mice, which correspondingly re-sensitises nociceptors." (PMID 33530940, 2021). "Thus, the present data exclude a role of TRPA1 in the colitis-related parameters under study." (PMID 32451393, 2020). "Since a contribution of TRPA1 to referred somatic pain that originates from inflamed visceral structures is not yet known, by pharmacological and genetic tool we explored a potential role of TRPA1 in the colitis-evoked referred hypersensitivity in the abdominal and periorbital skin areas." (PMID 32451393, 2020). "The search terms used were "Transient Receptor Potential Channels", "TRP channels", "TRPV1", "TRPA1", "TRPV4", "TRPV2", "TRPM2", "TRPM3", "TRPM7", "TRPM8", "TRPC3", "colitis", "inflammatory bowel disease", "IBD", "ulcerative colitis", "Crohn Disease"." (PMID 41096659, 2025). "In a rat model of TNBS colitis, the combination of TRPV1 antagonist BCTC and TRPA1 antagonist TCS-5861528 was found to significantly reduce visceral hypersensitivity when compared to the injection of the compounds separately, indicating a synergistic effect." (PMID 38731999, 2024). "Therefore, TRPA1 may play a protective or destructive role in colitis." (PMID 38659380, 2024). "Our results demonstrated that DSS colitis upregulated SP, HA, BK, PGI2, and 5-HT expression in the skin and increased TRPV1, TRPA1, and TH in L6 DRG, implying that DSS promoted surface neurogenic inflammation evoked by sympathetic-sensory coupling in skin-DRG." (PMID 36910013, 2023). "In contrast, the IL-1β expression in macrophages was suppressed by the TRPA1 agonist cinnamaldehyde and the TRPA1 agonist cannabinoid reduces INF-γ in macrophages by inhibiting nitric oxide (NO), thus exerting an anti-inflammatory role in colitis in mice." (PMID 37834182, 2023). "Given the importance of TRPA1 and TRPV1 nociceptive sensory neurons in colitis-mediated nociception, the targeted inhibition of these nociceptors can be a promising therapeutic strategy for alleviation of IBD-associated pain." (PMID 36076974, 2022). "In the same study, TRPA1 agonist 2,4,6-trinitrobenzene-sulfonic-acid (TNBS) was used for induction of colitis in mice." (PMID 36076974, 2022). "They claimed that CPZ activates TRPA1 in DRG neurons and the rectal administration of CPZ systemically desensitizes TRPA1/TRPV1 expressing peptidergic sensory neurons and attenuates pain and DSS-induced colitis in mice." (PMID 36076974, 2022). "Colitis rats supplemented with 12 mg CAP/kg bw for 4 weeks decrease serum IL-6 levels and protein expression of TRPV1 and TRPA1 in the colon, and increase serum SOD and CAT activities and colonic IL-10 levels." (PMID 35269566, 2022). "The induction of colitis with TNBS leads to oxidative stress generation, which, by TRPA1 activation, results in hypersensitivity to visceromotor response." (PMID 35562920, 2022). "Evidence exists on the use of TRPA1 agonists, Allyl isothiocyanate (AITC), and formalin, to induce colitis in rodents." (PMID 36076974, 2022). "It has been shown that TRPA1 contributes to colorectal contraction and visceromotor response after administration of allyl isothiocyanate (AITC) in a colitis model induced by 2,4,6-trinitrobenzenesulfonic acid (TNBS)." (PMID 35562920, 2022). "The constitutive expression of TRPA1 mRNA and protein in mouse and human primary CD4+ T cells controls CD4+ T cell activation and pro-inflammatory responses in models of colitis." (PMID 34041030, 2021). "Thus, the role of TRPA1 in colitis could be either protective or damaging." (PMID 32153564, 2020). "In order to explore the contribution of TRPA1 to this colitis-related hypersensitivity, DSS-treated mice received the selective TRPA1 antagonist HC-030031 or its vehicle." (PMID 32451393, 2020).
colitis (continued). "One conclusion is that TRPA1 expressed by DRG neurons supplying the colon is the prime factor that initiates referred pain and central sensitization in response to colitis." (PMID 32451393, 2020). "In order to further explore the possible contribution of TRPA1 to DSS-induced colitis, we tested the effect of genetic deletion of TRPA1 by examining the severity of colitis in Trpa1+/+ and Trpa1−/− mice." (PMID 32451393, 2020). "In a rat model of colitis, TRPV1 and TRPA1 synergistically interacted in the modulation of inflammation-induced visceral hypersensitivity." (PMID 31370176, 2019). "In accordance with this, we have found that TRPA1 and the pro-inflammatory neuropeptide SP in extrinsic primary afferent neurons are fundamental for the development of TNBS colitis." (PMID 29467763, 2018). "Our findings provide novel insight into the molecular mechanisms that lead to colitis attenuation by CPZ and strengthen the crucial role of TRPA1 as a gatekeeper for inflammation." (PMID 27356469, 2016). "Wild-type mice with oil of mustard (OM)-induced colitis have been reported to show an increase in levels of neuronal TRPA1, while TRPV1 activation in the colon was not significant." (PMID 38731999, 2024). "In addition, TRPA1 was also detected in CD4+ T-cells infiltrating colon tissue samples from patients with UC and CD, and TRPA1 is involved in the control of CD4+ T-cell activation and proinflammatory responses in two different T-cell-mediated colitis models." (PMID 37039840, 2023). "Although neuronal TRPA1 increases acute inflammation, non-neuronal TRPA1 activation is anti-inflammatory, and TRPA1 in CD4+T cells reduces T cell-mediated colitis." (PMID 36875034, 2023). "We assume that this role of TRPA1 takes place primarily at the primary sensory neuron level because the severity of colitis is not affected by TRPA1 blockade or deletion." (PMID 32451393, 2020). "TRPA1 could contribute to colorectal contraction and enhanced VMR to intracolonic AITC, which were detectable in TNBS-induced colitis." (PMID 32153564, 2020). "Different IBD models as well as the stage of the disease could also be the source of these contradictions, AITC induced IBD, indicates TRPA1 has having pro-inflammatory properties, as does the TNBS induced model of colitis." (PMID 33193423, 2020). "This colitis-related mechanical hypersensitivity of the periorbital region was absent in Trpa1−/− mice (P < 0.01 by two-way ANOVA)." (PMID 32451393, 2020). "Bertin and co-workers proposed non-neuronal TRPV1 and TRPA1-mediated proinflammatory mechanisms in colitis." (PMID 30935063, 2019). "An upregulation of NK1 receptor mRNA was reported in a mustard oil (MO) induced colitis in WT mice, but actions of MO in the lack of functional TRPA1 were not evaluated." (PMID 25265225, 2014). "OM colitis has a vital neuronal component, as evidenced by elevated expression of mu- and delta-opioids, and the receptors NK1, cannabinoid receptor 1 (CB1R) and TRPA1, the receptor for OM and a member of the transient receptor potential channel family." (PMID 20615234, 2010). "Another study has suggested that SP release from sensory neurons expressing TRPV1 or TRPA1 may contribute to the progression of DSS-induced colitis, wherein CGRP provides protection against colon inflammation independently of TRPV1 and TRPA1 expression on sensory neurons." (PMID 38731999, 2024). "Besides TRPA1/TRPV1, TRPM8 is also functionally expressed by the colon-innervating DRG neurons and TRPM8 expression is upregulated in inflamed colon samples from both human and mouse models of DSS- and TNBS-induced colitis." (PMID 36459135, 2023). "Colitis rats induced by 5% DSS and supplemented with 100 mg LBP/kg bw for 4 weeks reduces serum lipid peroxidation substance MDA levels, colonic TNF-α, serum IL-6 levels, and the expression of pain signaling proteins TRPV1 and TRPA1 in the colon, and enhance serum antioxidative CAT activity." (PMID 35269566, 2022).
colitis (continued). "In the present study, however, we found that the TRPA1 antagonist HC-030031 as well as genetic deletion of TRPA1 failed to significantly alter the severity of DSS-induced colitis as judged by body weight, colon length, colon weight, colonic MPO activity and disease activity score." (PMID 32451393, 2020). "Furthermore, DSS-induced colitis led to upregulation of TRPA1 mRNA in DRGs but not TGs, which suggests that TRPA1-expressing trigeminal sensory neurons do not contribute to the mechanical hyperalgesia seen in the periorbital skin." (PMID 32451393, 2020). "Likewise, the effect of TNBS-induced colitis to enhance spinal neuron activation and the visceromotor pain reaction to colorectal distension is absent in TRPA1 knockout mice." (PMID 21420431, 2011). "Here we confirm that pharmacologic blockade of TRPA1 with HC-030031 and genetic deletion of TRPA1 has no overt effect on the severity of DSS-induced colitis in mice." (PMID 32451393, 2020). "A recent paper has shown that both TRPV1 and TRPA1 are pro-inflammatory in nature and act in a similar manner (not antagonistic manner as claimed) in DSS-induced colitis using TRPA1 and TRPV1 knockout mice." (PMID 31488616, 2019). "In this study we show that TRPA1 agonism, rather than TRPV1 inhibition, in colonic sensory neurons is the key initial step in colitis protection by CPZ enemas." (PMID 27356469, 2016). "However, the contribution of TRPA1 to different types of inflammation may not be as prevalent as that of TRPV1, with recent reports suggesting the severity of colitis induced by TNBS is unaffected by TRPA1 deletion." (PMID 27713376, 2010).
Pruritus (34 papers, 2015 to 2026). Pruritus is an itch or a sensation that makes a person want to scratch. "It has been reported that IL-13 highly stimulates TRPA1 expression in mast cells and IL-31-induced pruritus decreased in TRPA1-deficient mice." (PMID 35563259, 2022). "Given the itch selectivity of IMQ in the mouse, we sought to determine whether IMQ+ neurons were part of a population of DRG neurons that encode TRPA1-dependent pruritus." (PMID 29561265, 2018). "Cytokines IL-4 and IL-13, primarily produced by Th2 cells and ILC2s (Group 2 Innate Lymphoid Cells), directly sensitize TRPA1 on sensory neurons, promoting pruritus." (PMID 41596464, 2026). "TSLP then acts as a master switch, targeting both TRPA1+ sensory neurons to evoke pruritus and FBs via TSLPR to activate Smad2/3 signaling and collagen synthesis, thereby directly linking epidermal sensing to dermal fibrosis." (PMID 41596464, 2026). "TRPA1 protein expression was also found to be increased in models of trigeminal neuropathy induced by IoNC and chronic dry skin itch evoked by acetone–diethylether–water (AEW), which were significantly inhibited following BoNT administration." (PMID 40864053, 2025). "CQ (25 μg/site)-induced moderate pruritus was also inhibited by the TRPA1 antagonist HC030031 (20 μg/site), showing the involvement of TRPA1 channels in the CQ response." (PMID 37441000, 2023). "miR-711 can directly bind the ion channel TRPA1 to elicit TRPA1-dependent itch, whereas neutralization of miR-711 is sufficient to inhibit pruritus after CTCL." (PMID 36520531, 2023). "Mechanistically, activation of IL-31RA has been shown to sensitize TRPV1 and TRPA1 ion channels for pruritus." (PMID 36520531, 2023). "The researchers also identified a specific subset of sensory neurons that require functional TSLP receptors and the ion channel TRPA1 to facilitate TSLP-evoked itch." (PMID 37834183, 2023). "To further demonstrate the association amongTmem100,Trpa1 andTrpv1, we compared neuron proportions and gene transcription levels between VEH mice and AEW pruritus mice through 10× single-cell RNA sequencing analysis." (PMID 36514220, 2022). "Although TRPV1 and TRPA1 are the major TRP ion channels that are directly involved in various types of pruritus, increasing evidence suggests that TRPV4 also plays an essential role in pruritus." (PMID 34925342, 2021). "In mice over-expressing TRG5, the exacerbated spontaneous scratching behavior was reduced by TRPA1 antagonists, thus supporting a coactivation of TGR5 and TRPA1 in BA induced pruritus." (PMID 33802836, 2021). "Further it was evidenced that both functional TSLPRs and TRPA1 channels are required for TSLP-induced pruritus." (PMID 33681256, 2021). "Accordingly, a recent study showed that TRPA1 knockout mice reveal a lower pruritus score by reducing the infiltration of mast cells, macrophages, as well as Th2 cytokine levels after challenge with 2,4-dinitrochlorobenzene." (PMID 34276687, 2021). "In conclusion, these results indicate that both channels, TRPV1 and TRPA1, are involved in the transmission of histamine-induced pruritus." (PMID 34439832, 2021). "Experiments revealed that IL-31 induces pruritus by binding to IL-31RA that is exclusively expressed on TRPV1+/TRPA1+ DRG neurons indicating TRP channels as key mediators of T-cell mediated IL-31-induced pruritus." (PMID 33681256, 2021). "Several studies presented evidence showing that TRPV1 and TRPA1 play crucial roles in pruritus transmission." (PMID 33681256, 2021). "Collectively, these data revealed an unconventional role of extracellular miRNAs as itch mediators and TRPA1 modulators and confirmed the biological relevance of this interaction in the pathophysiology of CTCL-associated itch." (PMID 33802836, 2021). "It is found that intradermal injection (i.d.)of Zn2+ dose-dependently induced acute itch and transient receptor potential A1 (TRPA1) participated in Zn2+-induced acute itch in mice." (PMID 35095413, 2021).
Pruritus (continued). "Overexpression of TRPA1 was observed in atopic and allergic contact dermatitis accompanied by chronic skin itching as well as inflammatory processes in the lungs, bronchi, and trachea." (PMID 32596360, 2020). "In an AD model induced by IL-13 in mice, the scratching behavior evoked by itch associated with increase in PGP9.5+, CGRP+, and TRPA-1+ (transient receptor potential ankyrin nerves, mast cells, and particularly in TRPA-1+ mast cells." (PMID 31619965, 2019). "Transient receptor potential vanilloid receptor 1 (TRPA1) is expressed in epidermal keratinocytes and in sensory neurons and plays an important role in pruritus pathogenesis." (PMID 28869563, 2017). "It was shown that certain thermosensitive TRP channels, especially TRP vanilloid 1 (TRPV1), TRPV3, TRPV4 and TRP ankyrin 1 (TRPA1), have important roles in the pathogenesis of pruritus as well as pain." (PMID 29140280, 2017). "In this study, wesubsequently examined the role of TRPV1 and TRPA1 in H2Sdonors-induced itch using pharmacological methods." (PMID 26602811, 2015). "IL-4 and IL-13 directly activate TRPA1+ sensory neurons via IL-4Rα, leading to chronic pruritus." (PMID 41596464, 2026). "Next, we further clarified whether Gper deficiency affects the function of the TRPA1 and TRPV1 in TG neurons under the AEW‐induced chronic itch condition." (PMID 37452499, 2023). "Combined with increased c-Fos expression in TMEM100+ neurons and TMEM100 expression in the AEW model, the TMEM100 protein could be a pivotal target for AEW itch alleviation through direct effects on itch-related TRPA1 function." (PMID 36514220, 2022). "Similarly, the induction of atopic dermatitis by topical application of oxazolone in mice induces milder atopic dermatitis symptoms, including pruritus, and lower levels of inflammatory cytokines and T-cell activation via TRPA1." (PMID 35562920, 2022). "Furthermore, cASCs and cASC-EVs ameliorated pruritus by reducing IL-31/TRPA1 through the inhibition of JAK-STATs signaling activation." (PMID 35563259, 2022). "Overall data show that, in psoriasis, TRPA1 exerts an anti-inflammatory role, and its activation, rather than inhibition, could lead to local control of skin inflammation and pruritus observed in both diseases." (PMID 35562920, 2022). "Transient receptor potential A1 (TRPA1) is mainly involved in non-histamine such as Il-31, Tslp-related pruritus, which is associated with pruritic transmission in the central nervous system." (PMID 36051905, 2022). "Moreover, cASCs or cASC-EVs reduced IL-31/TRPA1-mediated pruritus and activation of JAK/STAT signaling pathway." (PMID 35563259, 2022). "Moreover, our results revealed that the mRNA expression levels of Trpa1, Trpv1, and Trpv4 were significantly increased in the DRGs of the dry skin-induced chronic itch model." (PMID 35095413, 2021). "Together, these results indicated that the TRPA1/GPR39/ERK axis mediated the zinc-induced itch and, thus, targeting zinc signaling may be a promising strategy for anti-itch therapy." (PMID 35095413, 2021). "Additionally, administering higher IMQ concentrations converts an equivalent number of neurons as high concentrations of AITC, suggesting that for TRPA1 agonists, eliciting pruritus or nociception is dependent more on stimulus intensity than identity." (PMID 29561265, 2018). "Acute pruritus and plasma extravasation were induced in mice by the intradermal injection of either compound 48/80 (C48/80), the Mas-related G protein-coupled receptor (Mrgpr) agonist chloroquine (CQ), or the transient receptor potential ankyrin 1 (TRPA1) agonist allyl isothiocyanate (AITC)." (PMID 37441000, 2023). "However, whether 5-HT/HTR7/TRPA1-mediated Ca2+ influx inhibits M/Kv7 currents and then contributes to 5-HT-induced itch remains to be determined." (PMID 32694980, 2020).